CTLA4 (cytotoxic T-lymphocyte associated protein 4)
Diseases named in the same sentence as CTLA4 in open-access papers (continued):
Sharing a sentence is not in itself a finding about the gene and the disease.
colitis (continued). "After antibiotic treatment and establishment of humanized gut microbiota from colitic-irAE patients and non-irAE patients, colitis only occurred in the colitic-irAE-FMT mice after combined anti-PD-1 and anti-CTLA-4 treatment." (PMID 36891304, 2023). "Although CD69−Tregs also product IL-10 and TGF-β1 and express immunosuppressive molecule such as ICOS, GITR, and CTLA-4, they failed to attenuate DSS-induced colitis and T-cell transfer-induced colitis." (PMID 30185773, 2018). "In line with the role of CD80+ cells in colitis, the inflammatory score was significantly lower in mice treated with anti-CD80 but was not affected in mice treated with anti-CTLA4." (PMID 25595911, 2015). "Notably, patients treated with a combination of anti-CTLA-4 and anti-PD-1 drugs who developed ICI-induced colitis overexpressed mucosal IL-1β (as well as IL-17), but not TNF-α, with a higher abundance of Bacteroides intestinalis." (PMID 36900420, 2023). "This issue is manageable, however, given that patients who develop or did not develop colitis after anti-CTLA-4 therapy have distinct microbial communities, IL-10−/− mouse models show Bifidobacteria may prevent colitis after anti-CTLA-4 therapy, and FMT may prove effective." (PMID 32487228, 2020).
renal cell carcinoma (251 papers, 2011 to 2026). "Immune checkpoint inhibitors (ICIs) targeting programmed cell death-1 (PD-1), programmed cell death-ligand 1 (PD-L1), and cytotoxic T-lymphocyte-associated antigen 4 (CTLA-4) have revolutionized the prognosis of advanced renal cell carcinoma (RCC)." (PMID 36983417, 2023). "Two studies analyze relationship between CTLA-4 SNPs and renal cell cancer (RCC) risk and reported results contradicting each other." (PMID 33519815, 2020). "In 2010, the FDA approved the first CTLA-4 inhibitor for the treatment of metastatic melanoma, then, PD-1 inhibitors were approved for the treatment of melanoma, renal cell carcinoma (RCC) and non-small cell lung cancer (NSCLC)." (PMID 41235221, 2025). "As such, these IC genes merit further exploration for their possible differential expression in cancer and their potential as immunotherapy targets in renal cell carcinomas, which are currently treated with PD-1 and CTLA-4-blocking therapeutics." (PMID 40788962, 2025). "Based on a study involving 198 patients with renal cell carcinoma (RCC) or metastatic melanoma (MM) treated with CTLA4 inhibitors, small bowel colitis was identified as the primary major toxicity, observed in 21% of patients." (PMID 38169638, 2024). "Immunotherapy involving immune checkpoint inhibitors (ICIs), such as anti-programmed cell death receptor/ligand 1 (PD-1/PD-L1) and anti-cytotoxic T lymphocyte-associated antigen 4 (CTLA-4) antibodies, plays a well-established role in the treatment of clear cell renal cell carcinoma (RCC)." (PMID 39548483, 2024). "Ipilimumab, which is the first FDA-approved ICI, and tremelimumab (CTLA-4 inhibiting agents) are usually prescribed for melanomas, renal cell carcinomas (RCC), non-small cell lung cancer (NSCLC), pleural mesotheliomas, and hepatocellular carcinomas (HCC)." (PMID 39258067, 2024). "For instance, approximately 90% of patients with renal cell carcinoma who received anti‐CTLA‐4 plus anti‐PD‐1 combination therapy experienced irAEs of certain grade." (PMID 37986680, 2023). "Recently, immune checkpoint inhibitor (ICI) based combination therapies, including anti-PD-1 antibody, nivolumab with anti-CTLA-4 antibody, and ipilimumab have become the primary treatment option for metastatic or unresectable renal cell carcinoma (RCC)." (PMID 37340017, 2023). "Our previous study showed that increased eosinophil proportion of ≥3.0% is an effective biomarker for predicting irAE occurrences in patients with renal cell carcinoma who received anti‐CTLA‐4 plus anti‐PD‐1 combination therapy." (PMID 37986680, 2023). "Checkpoint inhibition therapies targeting PD-L1 or CTLA-4 pathways have shown promising effects in patients with renal cell carcinoma." (PMID 37780849, 2023). "Currently, the antibodies targeting the PD-1 and CTLA4 immune checkpoints have been successful in renal cell carcinoma." (PMID 36247009, 2022). "Ipilimumab (anti-CTLA-4 antibody) is a typical candidate for renal cell carcinoma (RCC) and melanoma therapy." (PMID 36423060, 2022). "In support of this idea, TAMs isolated from human renal cell carcinoma were previously able to induce CTLA4 expression in CD4+ T cells." (PMID 35418199, 2022). "Most immunotherapeutic agents being approved are for the treatment of renal cell carcinoma and bladder cancer, which mainly involve PD-1/PD-L1 and CTLA-4 pathways." (PMID 35626064, 2022). "The immune-related genes BIRC5, INHBE, and IL20RB were upregulated in a TMBhigh group and were associated with a poor prognosis, and a combination of PD-1 and CTLA-4 blockers was suggested for the treatment of advanced renal cell carcinoma with aberrations." (PMID 34795663, 2021). "Murine tumour models (mesothelioma, renal cell carcinoma) were treated with anti-CTLA-4 and anti-PD-L1 therapy then tumours and TDLN assessed for immune cell infiltration and profiling." (PMID 34141724, 2021). "In 2018, anti-CTLA4 (ipilimumab) plus nivolumab was approved by the FDA for renal cell carcinoma treatment." (PMID 34555656, 2021).
renal cell carcinoma (continued). "In a clinical trial of renal cell carcinoma patients treated with anti-PD1 or anti-PD-L1 alone, or in combination with anti-CTLA4, PBRM1 mutation is related with a higher ORR and longer survival." (PMID 33409155, 2020). "CTLA-4 blockade has also been shown to be active in patients with renal cell carcinoma and in patients with NSCLC." (PMID 25941561, 2015). "In the treatment of malignant tumors such as renal cell carcinoma and prostate cancer, the FDA-approved immune checkpoint inhibitors Ipilimumab and Tremelimumab, which target CTLA-4 (cytotoxic T-lymphocyte-associated protein 4), have demonstrated potent anti-tumor effects by targeting Treg cells." (PMID 40428349, 2025). "In the 112-patient CheckMate 214 trial focusing on the International Metastatic Renal Cell Carcinoma Database Consortium (IMDC) intermediate- and poor-risk group, nivolumab plus ipilimumab, a CTLA-4 binder, showed improved efficacy with an ORR of 57% compared to just 19% with sunitinib alone." (PMID 39564030, 2024). "However, the hypomethylation of CTLA‐4 promoter biomarker was found to have favorable outcomes in renal cell carcinoma patients treated with immune checkpoint blockade." (PMID 38894611, 2024). "PLOD2 was related to HNSCC, hepatitis C, hepatocellular carcinoma, renal cell carcinoma, and CTLA4 inhibitory signaling while PLOD3 was linked to basal cell carcinoma, renal cell carcinoma, ncRNAs involved in WNT signaling in hepatocellular carcinoma, and FRS-mediated FGFR2 signaling." (PMID 36820030, 2023). "CTLA-4 is the second target of checkpoint inhibition therapies in renal cell carcinoma." (PMID 31137694, 2019). "The prognosis of patients with metastatic renal cell carcinoma (RCC) has improved with the introduction of novel combination therapies, including monoclonal antibodies such as ipilimumab (against CTLA-4) with nivolumab (against PD-1)." (PMID 41988182, 2026). "Thus, deletion of the IFN gene cluster might be potentially used as a prognostic biomarker for anti-CTLA4 immunotherapy resistance in renal cell carcinoma as well." (PMID 34555656, 2021). "Immunotherapy-based combinations, driven by PD-1, PD-L1, and CTLA-4 inhibitors, has altered the treatment landscape for metastatic renal cell carcinoma (RCC)." (PMID 32961934, 2020). "Previous studies in the Chinese population showed a significant relationship between CTLA-4 +49A/G and bladder cancer and a significant relationship between CTLA-4 CT60 and renal cell cancer in the Spanish population." (PMID 38046481, 2023). "Beyond the CTLA-4/CD80-86 pathway, other inhibitor receptors have been identified as interesting immune checkpoints in renal cell carcinomas." (PMID 36551715, 2022). "Moreover, in multivariable Cox regression, CTLA4 promoter hypomethylation remained an independent predictor of improved outcome in ICB-treated ccRCC after co-adjustment of the International Metastatic Renal Cell Carcinoma Database Consortium score (HR 3.00 (95% CI 1.47 to 6.28), p=0.003)." (PMID 34446578, 2021). "Ipilimumab, a monoclonal antibody against CTLA-4, demonstrates response rates between 5–12.5%, but no complete responses or durable regressions were seen in renal cell carcinoma." (PMID 35127542, 2022). "The advent of checkpoint inhibitors has revolutionized the systemic treatment of many malignancies, including renal cell carcinoma (RCC), and in clinical trials, a variety of PD-1, PD-L1, and CTLA-4 inhibitors have been shown to respond to patients and improve patient survival." (PMID 33517850, 2021). "Some examples include anti-PD-1/PD-L1 and anti-CTLA4 inhibitors, which have been shown to be effective for treating melanoma, non-small cell lung cancer (NSCLC), renal cell carcinoma (RCC), breast carcinoma (BC) as well as other cancers." (PMID 41438767, 2025).
renal cell carcinoma (continued). "Another retrospective study of patients with renal cell carcinoma (RCC) bone metastases treated with ipilimumab/nivolumab found relatively low efficacy (21%) and median OS (25.6 months), and, generally, patients with bone metastases responded poorly to the combination of PD-1 and CTLA-4 inhibitors." (PMID 38464516, 2024). "Clinical benefits of ICIs that target CTLA-4, PD1/PD-L1 have been observed in various advanced tumors, such as renal cell carcinoma (RCC), cutaneous squamous cell cancer, melanoma, head and neck cancer, and NSCLC." (PMID 35450073, 2022). "For example, ipilimumab, a mAb that targets CTLA-4, was certified as a iICP inhibitor in order to treat metastatic melanoma, MSI-H/dMMR CRC, and renal cell carcinoma (RCC)." (PMID 36275750, 2022). "Similarly, upregulation of SLC2A3 could enhance CD28 costimulation reprogrammed renal cell carcinoma CD8+ TIL metabolism, which is antagonized by the inhibitory and checkpoint immunotherapy receptors CTLA4 and PD-1." (PMID 36247875, 2022). "In renal cell carcinoma (RCC), BsAbs target ENPP3 × CD3, HER2 × HER3, and PD-1 × CTLA-4." (PMID 40260236, 2025). "Immune-checkpoint inhibitors (ICI) are increasingly used as single agents (e.g., anti-CTLA-4, PD-1, and PDL-1) or as combined/dual agent therapy alongside SRS for the treatment of NSCLC, melanoma, renal cell carcinoma (RCC), and other histologies of brain metastases." (PMID 37173897, 2023). "Drugs targeting CTLA4 and the PD1 pathway have since been applied to a wide range of tumor types including lymphoma, lung cancer, renal cell carcinoma (RCC), head and neck squamous cell carcinoma (HNSCC), bladder cancer, liver cancer, breast cancer, and gastro-esophageal cancer." (PMID 34868044, 2021). "Although PH may be a rare complication of combined anti-CTLA-4 and anti-PD1 immunotherapy, it is nevertheless of importance given the fact that this treatment modality is increasingly used also in adjuvant settings and other malignancies such as colorectal cancer and renal cell carcinoma." (PMID 30376886, 2018).
glioma (243 papers, 2008 to 2026). A benign or malignant brain and spinal cord tumor that arises from glial cells (astrocytes, oligodendrocytes, ependymal cells). "The expression of immune checkpoint molecules such as programmed death-ligand 1 (PD-L1) and cytotoxic T-lymphocyte-associated protein 4 (CTLA-4) is markedly increased in gliomas, inhibiting the activity of effector T cells and inducing the expansion of Tregs." (PMID 40343558, 2025). "Upregulation of PD-1, PD-L1, and CTLA-4 within the glioma TME is associated with advanced disease stage and poorer survival, even independent of therapeutic intervention." (PMID 41346390, 2025). "Researchers have proved that the inhabitation of IDO, CTLA‐4, and PD‐L1 interacted with increased Treg‐associated long‐term survival in gliomas." (PMID 37953502, 2024). "Although anti-PD-1/PD-L1 and Cytotoxic T-lymphocyte-associated antigen 4 (CTLA-4) monoclonal antibodies are studied extensively in glioma, most are in phase I or phase II clinical research stages." (PMID 38404571, 2024). "The study found that lower CTLA4 expression in glioma patients was associated with significantly extended overall survival, underscoring its potential as a valuable prognostic marker." (PMID 39409893, 2024). "While the focus is primarily on immune checkpoints like the programmed cell death protein 1 (PD1) and cytotoxic T lymphocyte-associated antigen 4 (CTLA4), scarce clinical trials conducted on ICIs for gliomas have yielded significant outcomes." (PMID 38956740, 2024). "Another inhibitory immune pathway is cytotoxic T lymphocyte-associated antigen 4 (CTLA-4), which is also viewed as a critical role in the aggressiveness of gliomas." (PMID 36776876, 2023). "Our founding showed that high expression of REST was positively linked to PD1, PD-L1, and CTLA-4 in glioma." (PMID 36810892, 2023). "We tested the drug response of gliomas to PD‐1 and CTLA‐4, and the results showed that high‐risk gliomas are highly responsive to PD‐1 immunotherapy, but poorly to CTLA‐4 immunotherapy." (PMID 35668574, 2023). "Although it has been shown that CTLA-4 positively correlates with immune-related proteins in glioma, excessive CTLA-4 expression is associated with a worse prognosis for glioma patients." (PMID 37351101, 2023). "In glioma, an upregulated expression of inhibitory checkpoint proteins, PD-1 (and its ligand PD-L1) and CTLA-4, have been associated with immune evasion, increased tumor grade and poor patient prognosis." (PMID 37046685, 2023). "The critical immune checkpoint targets for ICIs in glioma include programmed cell death protein-1 (PD-1), programmed cell death ligand-1 (PD-L1), and cytotoxic T-lymphocyte-associated antigen 4 (CTLA-4)." (PMID 35406398, 2022). "Immune checkpoints such as TIGIT, CTLA-4, PD-1 on T cells are thought to cause T cell exhaustion and associate with glioma recurrence." (PMID 35711434, 2022). "Preclinical studies have shown that blocking programmed cell death protein-1 (PD-1) or cytotoxic T lymphocyte-associated antigen-4 (CTLA-4) can significantly inhibit the growth of glioma cells and prolong the survival time of experimental animals." (PMID 35982954, 2022). "The results exhibited an intimate connection between ITGA5 and most immune checkpoint molecules in gliomas, especially in programmed cell death 1 (PD-1), programmed cell death 1 ligand 1 (PD-L1), and cytotoxic T-lymphocyte associated protein 4 (CTLA-4)." (PMID 35371978, 2022). "Patients with glioma have been found to express CTLA-4, and this expression has been implicated in glioma progression." (PMID 36146527, 2022). "We then examined the correlation between risk scores and ICIs (PD1, PDL1, CTLA4, and B7-H3) in gliomas." (PMID 35647198, 2022). "Since then, a diverse set of biomarkers have been implicated as prognostic indicators in gliomas, including checkpoint molecules (PD-1, CTLA-4, TIM-3), growth/angiogenesis proteins (EGFR), and cytokines (TGF-β, IL-4, IL-13)." (PMID 35203944, 2022).
glioma (continued). "High expression of classical ICGs like CTLA4 was also noticed in high-risk glioma samples, implying its immunosuppressive microenvironment." (PMID 34603309, 2021). "A higher expression of CTLA-4 was observed in more severe grades of glioma, and this indicates that it is linked to a worse prognosis." (PMID 34305910, 2021). "According to our gene model, the expression level of PD- L1, PD-1, and CTLA-4 was lower in glioma patients with a high risk score (P < 0.05)." (PMID 34804978, 2021). "We analyzed the expression of CTLA-4 in glioma according to WHO grade, IDH mutation status, and different subtypes in TCGA and CGGA databases." (PMID 31911758, 2020). "miR-138 exerts anti-glioma efficacy by targeting the immune checkpoints T-lymphocyte-associated antigen 4 (CTLA-4) and programmed cell death protein 1 (PD-1)." (PMID 32122338, 2020). "•PD-1, PD-L1, PD-L2, and CTLA4 DNA methylation in lower-grade gliomas is associated with age and mutation status." (PMID 29396294, 2018). "GB-derived exosomes have limited ability to activate CD8+ T lymphocytes yet it has been reported that the expression of CD86 on glioma cell lines can be bound competitively by cytotoxic T-lymphocyte-associated protein 4 (CTLA-4), leading to possible T cell immunosuppression." (PMID 36467419, 2022). "Gliomas possessing IDH mutations expressed lower CTLA-4 in TCGA database." (PMID 31911758, 2020). "We found that all of these molecules were tightly associated with CTLA-4 in patients with glioma." (PMID 31911758, 2020). "Additionally, downregulation of CTLA-4 on peripheral lymphocytes is associated with an improved prognosis in patients with glioma." (PMID 30619286, 2018). "Moreover, higher CTLA-4 expression was associated with worse prognosis in patients with gliomas." (PMID 31911758, 2020). "Although anti–PD-1 and anti–CTLA-4 targeting antibodies, so far, have been ineffective in the treatment of gliomas, combining known immune checkpoint blockades with novel targets remains a promising strategy." (PMID 39378431, 2025). "As a member of the TGFβ superfamily, GDF15 targets CTLA4, a key immune checkpoint protein, thereby promoting glioma progression." (PMID 40535121, 2025). "Preclinical glioma studies show that CTLA-4 inhibitors promote CD4+ T cell proliferation and reduce Treg/CD4+ T cell ratios, correlating CTLA-4 expression with poor prognosis in glioblastoma." (PMID 39911397, 2025). "Preclinical studies show that dual CTLA-4/PD-1 blockade can be synergistic, curing 75% of murine gliomas but clinical translation is challenging." (PMID 41583467, 2025). "With the anti-CTLA-4 and the anti-PD-1 treatment, all the “responsive” and “partially responsive” models demonstrated statistical decrease in the percentage of Ki67+ glioma cells in comparison with corresponding untreated controls." (PMID 39851525, 2025). "Multiple levels of suppression are produced by the upregulation of other immune checkpoint molecules in glioma-infiltrating lymphocytes, including TIM-3, LAG-3, VISTA, and cytotoxic T-lymphocyte-associated protein 4 (CTLA-4)." (PMID 41583467, 2025). "The PD-L1/PD-1 axis (CD274/PDCD1) and CTLA4 are currently considered core targets in glioma immunotherapy." (PMID 40661083, 2025). "The FDA-approved combination of nivolumab and ipilimumab for hepatocellular carcinoma has shown promising preclinical results in glioma models, where CTLA-4 and PD-1 blockade significantly extended survival, with 74% of mice achieving long-term responses." (PMID 39911397, 2025). "For instance, therapeutic inhibition of PD-L1 or CTLA-4 significantly reduced the number of tumor-infiltrating Treg cells and improved long-term survival in mouse glioma models." (PMID 41035644, 2025). "In a glioma model, administration of miR-138 substantially reduces the expression of CTLA-4, PD-1, and Foxp3 on CD4+ T cells that infiltrate the tumor." (PMID 38726321, 2024).